MOSPD2 (motile sperm domain containing 2)
Description:
Endoplasmic reticulum-anchored protein that mediates the formation of contact sites between the endoplasmic (ER) and endosomes, mitochondria or Golgi through interaction with conventional- and phosphorylated-FFAT-containing organelle-bound proteins. In addition, forms endoplasmic reticulum (ER)-lipid droplets (LDs) contacts through a direct protein-membrane interaction and participates in LDs homeostasis. The attachment mechanism involves an amphipathic helix that has an affinity for lipid packing defects present at the surface of LDs. Promotes migration of primary monocytes and neutrophils, in response to various chemokines.
Synonyms: MGC26706
Tractability: Antibody: its Gene Ontology location is reachable by antibodies, with high confidence; UniProt predicts a signal peptide or a membrane-spanning region. PROTAC: ubiquitination databases record sites on it; its protein half-life has been measured.
Gene: Protein-coding gene on chromosome X (14,873,421 to 14,922,327, forward strand). Ensembl gene ENSG00000130150.
Subcellular location: Endoplasmic reticulum membrane
Subcellular location (Human Protein Atlas): Endoplasmic reticulum
Pathways (Reactome):
Immune System: Neutrophil degranulation
Signal Transduction: RHOD GTPase cycle
Gene Ontology:
Molecular function: FFAT motif binding; protein binding
Biological process: lipid droplet formation; positive regulation of monocyte chemotaxis; positive regulation of neutrophil chemotaxis; protein homooligomerization
Cellular component: endoplasmic reticulum; endoplasmic reticulum membrane; endoplasmic reticulum-endosome membrane contact site; membrane; organelle membrane contact site; plasma membrane; endomembrane system; specific granule membrane
Homologues: Orthologues: chimpanzee MOSPD2 (99% identical), macaque MOSPD2 (98% identical), dog MOSPD2 (94% identical), pig MOSPD2 (90% identical), mouse Mospd2 (90% identical), rat Mospd2 (90% identical), guinea pig MOSPD2 (88% identical), rabbit MOSPD2 (88% identical), tropical clawed frog mospd2 (62% identical), zebrafish mospd2 (61% identical), Caenorhabditis elegans hpo-28 (26% identical), Drosophila melanogaster CG33523 (25% identical), and 1 more.
Diseases named in the same sentence as MOSPD2 in open-access papers:
MOSPD2 is named in the same sentence as 14 diseases in open-access papers, as found by Europe PMC text mining. Sharing a sentence is not in itself a finding about the gene and the disease. The quoted sentences say what the papers report.
breast carcinoma (1 paper, 2020). "MOSPD2 encodes motile sperm domain-containing protein 2 and has recently been reported to promote the metastasis of breast cancer." (PMID 32087735, 2020).
epilepsy (1 paper, 2021). A brain disorder characterized by episodes of abnormally increased neuronal discharge resulting in transient episodes of sensory or motor neurological dysfunction, or psychic dysfunction. "As it has been demonstrated silencing or neutralizing MOSPD2 not only reduced the proportion of inflammatory monocytes in the blood significantly but also inhibited monocyte migrating into CNS, MOSPD2 may be a potential target for the treatment of epilepsy." (PMID 34555062, 2021).
infertile (1 paper, 2019). "Altogether, these findings will delineate the significance of MOSPD2 auto-antigen in a bacteria derived immune infertility condition." (PMID 32743492, 2019). "RIEP was performed to confirm Lmb mimicked MOSPD2 antigen as a sperm as well as bacteria antigen against the ASAs produced in the seminal plasma of an infertile LCS/BS sample." (PMID 32743492, 2019).
male infertility (1 paper, 2019). The inability of the male to effect fertilization of an ovum after a specified period of unprotected intercourse. "However, in-depth investigation is necessary to determine specific autoantibodies binding to MOSPD2 auto-antigen, and their exact localization on spermatozoa can reveal many secrets associated with male infertility." (PMID 32743492, 2019).
metastatic tumors (1 paper, 2022). "The IHC results showed that the expression of MOSPD2 was reduced in metastatic tumors formed by EBV-miR-BART-22 compared with metastatic tumors formed by control cells." (PMID 35907914, 2022).
osteoporosis (1 paper, 2024). A condition of reduced bone mass, with decreased cortical thickness and a decrease in the number and size of the trabeculae of cancellous bone (but normal chemical composition), resulting in increased fracture incidence. "Our study systematically identified seven candidate hub genes (PDP1, ALS2CL, VLDLR, PLEKHA6, PPP1CB, MOSPD2, and METTL9) through a combination of various bioinformatics analyses and machine learning algorithms, and provided a nomogram for diagnosing sarcopenia associated with osteoporosis." (PMID 38831425, 2024). "We identified 7 candidate hub genes (PDP1, ALS2CL, VLDLR, PLEKHA6, PPP1CB, MOSPD2, METTL9) and constructed column line plots for osteoporosis combined with sarcopenia." (PMID 38831425, 2024). "A notable finding is the identification of 7 key candidate genes (PDP1, ALS2CL, VLDLR, PLEKHA6, PPP1CB, MOSPD2, and METTL9), and the development of a nomogram for diagnosing osteoporosis in sarcopenia patients." (PMID 38831425, 2024).
infection (3 papers, 2023 to 2025). The state of being infected such as from the introduction of a foreign agent such as serum, vaccine, antigenic substance or organism. "Future work could focus on detailing whether MOSPD2 association in monocytes impacts cell migration upon infection with Toxoplasma." (PMID 37341482, 2023). "Fourth, most MOSPD2 associating with the PVM is newly translated after infection of the cell and requires the major functional domains of MOSPD2, identified as the CRAL/TRIO domain and tail anchor, although these domains were not sufficient for PVM association." (PMID 37341482, 2023). "Other genes that increased infection efficiency by ≥4-fold upon knockout included MOSPD2, P4HB, and LY6E (each leading to an approximately 4-fold increase) and IRX2 (an approximately 8-fold increase)." (PMID 40901862, 2025). "Although the major difference in MOSPD2 association seen during infection is between RH/ME49 and CTG/Nc, RH and ME49 also appear to differ in the pattern of MOSPD2 association at the PVM." (PMID 37341482, 2023). "In particular, MoSPD2 was expressed mainly at late time points of infection (e.g., 60 to 72 hpi), while MoSPD3/MoBAS52 was more expressed at the early time points (e.g., 24 to 32 hpi)." (PMID 38298608, 2023). "Another possibility is that MOSPD2 association at the PVM could be related to the immune response and so its function will only be revealed when infection of a cell type other than HFFs is examined or when cells are stimulated by cytokines like IFN-γ." (PMID 37341482, 2023). "Similarly, mutant parasites in ROP1, ROP5, ROP18, TGGT1_247350, and GRA12 showed no change in host MOSPD2 association at the PVM relative to infection with RH-wild type." (PMID 37341482, 2023).
cancer (2 papers, 2020 to 2022). A tumor composed of atypical neoplastic, often pleomorphic cells that invade other tissues. "MOSPD2, which is expressed on the plasma membrane of human monocytes, was explored for its potential to regulate cancer cell migration and metastasis." (PMID 35907914, 2022). "The GEO arrays (GSE118719) also showed low expression of MOSPD2 in carcinoma tissues." (PMID 35907914, 2022). "MOSPD2 is a beneficial protein in NPC, and this finding is in contrast to that of a previous study of cancer showing that MOSPD2 promotes cancer migration." (PMID 35907914, 2022). "The other five genes (i.e. PPP1R15A, MOSPD2, FAM84B, GARS, KIF21B) have demonstrated involvement in the progression of various cancers." (PMID 32087735, 2020).
MOSPD2 also shares sentences with these, for which no sentence is quoted: Alpha-thalassemia (1 paper); anemia (1); Diamond-Blackfan anemia (1); Fanconi anemia (1); microcytic anemia (1); sarcopenia (1).